SSX2B (SSX family member 2B)
Description:
Could act as a modulator of transcription.
Synonyms: CT5.2; CT5.2b; HOM-MEL-40; SSX
Gene: Protein-coding gene on chromosome X (52,751,132 to 52,790,305, forward strand). Ensembl gene ENSG00000268447.
Subcellular location: Nucleus
Subcellular location (Human Protein Atlas): Nucleoli; Nucleoplasm
Gene Ontology:
Molecular function: protein binding
Biological process: regulation of DNA-templated transcription
Cellular component: nucleus
Homologues: Orthologues: mouse Ssxb9 (34% identical), mouse Ssxb8 (33% identical), mouse Ssxb6 (32% identical), mouse Ssxb1 (32% identical), mouse Ssxb10 (32% identical), mouse Ssxb15 (32% identical), rat Ssx2 (32% identical), mouse Ssxb13 (31% identical), mouse Ssxb3 (31% identical), rat Ssx1 (31% identical), mouse Ssxb14 (31% identical), mouse Ssxb5 (30% identical), and 3 more. Paralogues in human: SSX2 (100% identical), SSX3 (90% identical), SSX7 (85% identical), SSX5 (84% identical), SSX4 (79% identical), SSX4B (79% identical), SSX1 (78% identical).
Diseases named in the same sentence as SSX2B in open-access papers:
SSX2B is named in the same sentence as 3 diseases in open-access papers, as found by Europe PMC text mining. Sharing a sentence is not in itself a finding about the gene and the disease. The quoted sentences say what the papers report.
infectious disease (1 paper, 2023). A disorder directly resulting from the presence and activity of a microbial, viral, or parasitic agent in humans. "TSPY4, OPN1LW, CARF, CCDC14, HNRNPCL4, SSX2B genes need further exploration as it has not been identified in any infectious disease, including the recent COVID-19 pandemic." (PMID 37644081, 2023).
SSX2B also shares sentences with these, for which no sentence is quoted: cancer (1 paper); synovial sarcoma (1).